NCOR2 (nuclear receptor corepressor 2)
Diseases named in the same sentence as NCOR2 in open-access papers (continued):
Sharing a sentence is not in itself a finding about the gene and the disease.
aortic valve stenosis (1 paper, 2022). Aortic valve stenosis (AVS) is a condition characterized by narrowing of the heart's aortic valve opening. "The finding indicates the mutations TTN, NUP205, and NCOR2 can enhance the severity of aortic valve stenosis, a consequence of BAV." (PMID 36071494, 2022).
autism (1 paper, 2021). Persistent deficits in social interaction and communication and interaction as well as a markedly restricted repertoire of activity and interest as well as repetitive patterns of behavior. "Furthermore, with specific relevance to the recent discovery of NCOA7 mutations in autism, several de novo genetic variants in the nuclear receptor corepressors NCOR1 and NCOR2 are found in pediatric patients with intellectual disabilities or ASD." (PMID 33340069, 2021).
autoimmune disease (1 paper, 2022). A disorder resulting from loss of function or tissue destruction of an organ or multiple organs, arising from humoral or cellular immune responses of the individual to their own tissue constituents. "Therefore, to associate if expression of Ncor2 is altered in autoimmune disease, we performed RT-qPCR of Ncor2 from peripheral blood mononuclear cells (PBMCs) of 11 RA patients and 14 healthy donors." (PMID 36238311, 2022).
chordoma (1 paper, 2013). Chordomas are rare malignant tumors arising from embryonic remnants of the notochord in axial skeleton. "Six genes (NOTCH2, NCOR2, CREBBP, JAG1, KAT2A and NCSTN) related to the Notch signaling pathway were upregulated in chordoma tissues." (PMID 23826111, 2013).
Crohn disease (1 paper, 2023). A gastrointestinal disorder characterized by chronic inflammation involving all layers of the intestinal wall, noncaseating granulomas affecting the intestinal wall and regional lymph nodes, and transmural fibrosis. "NCOR2, NFATC4 and PAXBP1 code for transcription-associated factors and their dysregulations are linked to Crohn's disease, carcinogenesis and myopathic hypotonia, respectively." (PMID 37026480, 2023).
epilepsy (1 paper, 2024). A brain disorder characterized by episodes of abnormally increased neuronal discharge resulting in transient episodes of sensory or motor neurological dysfunction, or psychic dysfunction. "NCOR2 mediates the transcriptional repression activity of some nuclear receptors by promoting chromatin condensation, thus preventing access to basal transcription and is a novel candidate gene for the migraine-epilepsy phenotype." (PMID 38379763, 2024).
giant cell tumor of soft tissue (1 paper, 2024). A painless, well circumscribed tumor arising in soft tissue, usually of the upper and lower extremities. "The authors reported a series of six cases similar to giant cell tumor of soft tissue (GCTST) but with a distinct predilection for appearing in young females, demonstrating keratin expression, and harboring a high mobility group AT-hook 2 (HMGA2)–nuclear receptor corepressor 2 (NCOR2) fusion." (PMID 38792018, 2024).
hepatitis C (1 paper, 2023). "Finally 6 genes (NCOR2, NR1H3, PPARA, IRF3, MAP2K3, and TLR6) were enriched in 3 immune-related pathways, including toll-like receptor signaling pathway, EB virus infection, and hepatitis C." (PMID 37845378, 2023).
Huntington disease (1 paper, 2016). Huntington disease (HD) is a rare neurodegenerative disorder of the central nervous system characterized by unwanted choreatic movements, behavioral and psychiatric disturbances and dementia. "It was interesting to note that genes involved in Huntington’s disease were enriched in this signature, namely MAP2K7, PDPK1, NCOR2, EP300, and REST." (PMID 27698411, 2016).
ischemia (1 paper, 2019). A hypoperfusion of the BLOOD through an organ or tissue caused by a PATHOLOGIC CONSTRICTION or obstruction of its BLOOD VESSELS, or an absence of BLOOD CIRCULATION. "However, experiment results in Mus Musculus showed that the increased expression of NCOR2 after LAD ligation surgery may be induced by negative feedback of reduced heart output at the onset of ischemia." (PMID 30949047, 2019).
leiomyoma (1 paper, 2024). A well-circumscribed benign smooth muscle neoplasm characterized by the presence of spindle cells with cigar-shaped nuclei, interlacing fascicles, and a whorled pattern. "Another study comparing uterine leiomyoma and leiomyosarcoma found that a small percentage (3 out of 56) of leiomyoma cases showed a RAD51B fusion (with HMGA2, NCOR2, and NUDT3), and one of these cases with RAD51B::NUDT3 fusion is reported here in detail." (PMID 37466765, 2024).
mesothelioma (1 paper, 2023). A usually malignant and aggressive neoplasm of the mesothelium which is often associated with exposure to asbestos. "In line with this, we found enrichment for ERGs (P value = 3.4 × 10−3), including the mesothelioma drivers NCOR2 and EZH2, among the genes highly expressed in CIMP-high tumors, and more generally in the list of MPM drivers (q value = 2.1 × 10−5)." (PMID 36928603, 2023).
migraine (1 paper, 2024). "The higher expression level of NCOR2 may lead to a ReHo increment by having a more inhibitory effect on gene transcription in migraine." (PMID 38379763, 2024).
myeloma (1 paper, 2021). "NCOR2 was previously reported to be down-regulated in MM cell lines and patient-derived myeloma cells and induces tumor cell proliferation, although the underlying mechanism is not fully understood." (PMID 34864816, 2021). "To define the role of NCOR2 in MM, we created NCOR2 knockout human myeloma cell lines and demonstrated that NCOR2 knockout led to high MYC expression." (PMID 34864816, 2021). "Here, we report a novel pathway involving NCOR2 mediated drug resistance in myeloma independent of CRBN." (PMID 34864816, 2021).
Nephropathy (1 paper, 2025). A nonspecific term referring to disease or damage of the kidneys. "As NCOR2 is involved in both renal lipid metabolism and inflammation, it is possible that regulation of this gene presents a novel pathway to development of APOL1 nephropathy in those with HIV." (PMID 39448372, 2025).
non‐alcoholic fatty liver disease (1 paper, 2020). "Another hub protein, NCOR2 has been reported to be associated with non‐alcoholic fatty liver disease, which is one of the prominent risk factors for cardiovascular disease." (PMID 32196466, 2020).
osteophytes (1 paper, 2016). "NCOR2 and CD36 genes were associated with induction of radiographic knee OA measured as either a K/L grading of ≥2.0 or the presence of osteophytes, while the polymorphisms at CILP, TNA, IL1RN and variation at inflmmatory genes appeared to correlate with radiographic progression over time." (PMID 27457563, 2016).
prostate tumors (1 paper, 2023). "Integrative genomic analysis of primary prostate tumors and associated LNM demonstrated the enrichment of mutations in several genes including both well-established oncogenes and tumor suppressors and understudied genes such as EYA1, CSMD3, FLT4, NCOR2, and PCDH15." (PMID 38067373, 2023).
pulmonary arterial hypertension (1 paper, 2023). Pulmonary arterial hypertension (PAH) is a group of diseases characterized by mean pulmonary artery pressure >20 mmHg and elevated pulmonary arterial resistance leading to right heart failure. "This approach was used in a paper from this year that shows significant upregulation of SOCS3, ITGAL, NFIC, NCOR2, and PGK1 mRNA (qRT-PCR) in peripheral blood mononuclear cells from pulmonary arterial hypertension (PAH) patients compared to healthy controls (p ≤ 0.05)." (PMID 37762023, 2023).
rheumatoid arthritis (1 paper, 2022). A chronic, systemic autoimmune disorder characterized by inflammation in the synovial membranes and articular surfaces. "We also depicted decreased Ncor2 expression in Rheumatoid Arthritis, a Th1/Th17 disease." (PMID 36238311, 2022).
serous carcinomas (1 paper, 2023). "Highest NCOR2 immunoreactivity was observed in serous carcinomas and was dependent on tumor grading." (PMID 37131060, 2023).
tumor (63 papers, 2007 to 2025). "The effect of PLANE on cancer proliferation and tumorigenicity is associated with a tumour-suppressive NCOR2 AS isoform (NCOR2-202)." (PMID 35427215, 2022). "Another 18 tumour-related genes such as NCOR2 and PALB2 were found to be mutated in BTG and PTCb only." (PMID 36686473, 2022). "The WES analyses detected mutations in KMT2C, KNL1, and NCOR2 genes in all the tumor samples (100%)." (PMID 34245124, 2021). "Further experiments are needed to verify the effect of the NCOR2 variant on tumor progression." (PMID 39309469, 2024). "Indeed, we found that PLANE-mediated suppression of NCOR2 expression was due to selective repression of AS production of the NCOR2-202 transcript that encodes one of the major NCOR2 protein isoforms, NCOR2 isoform 236, demonstrating a tumour suppressive function of this isoform." (PMID 34145290, 2021). "Our study findings support BQ323636.1 (BQ), a splice variant of NCOR2, as a key orchestrator of such metabolic reprogramming, driving lipid metabolism via ACSL4 to support tumor growth, survival, and resistance in ER-positive breast cancer." (PMID 40507798, 2025). "NCOR2 enables tumor cells to evade immune surveillance by suppressing MHC class I expression and impairing CD8+ T cell activity, thereby promoting metastasis; notably, high NCOR2 expression correlates with shortened metastasis-free survival in BC." (PMID 41019979, 2025). "Histopathological analysis revealed a mesenchymal tumour harbouring a novel NCOR2(exon 7)::GLI1(exon 6) gene fusion." (PMID 41035732, 2025). "The most affected oncogenic signaling pathways in our NB tumor samples were RTK-RAS, NOTCH, and Hippo, which are linked to primary mutations in ALK, NCOR2, and FAT2, respectively." (PMID 39338204, 2024). "We found six heterozygous variants predicted to alter splicing; two in DNA repair-associated genes (BRCA1 and BAP1) and four in tumor suppressor genes (ARHGEF10L, ELL, MYH9, and NCOR2)." (PMID 37234870, 2023). "In conclusion, significant heterogeneity exists in the roles of NCOR2 in different types of tumours." (PMID 36497280, 2022). "Previous studies have shown that nuclear receptor corepressor 2 (NCOR2) plays a vital role in neurodevelopment and in various tumours." (PMID 36497280, 2022). "There are both suppressor genes and tumor oncogenes mutated in all nine/nine parts of the tumor, such as EP300 and NCOR2 (NOTCH), PTEN (PI3K), EGFR (RTK-RAS) and FAT1 (Hippo)." (PMID 33922652, 2021). "High MYC expression in tumor cells of MM patients has been shown to corelate with poor prognosis, suggesting the correlation of low NCOR2 and poor prognosis." (PMID 34864816, 2021). "There are mutated tumor suppressor genes in all (nine/nine) tumor portions, such as EP300 and PTEN in GB01, NCOR2 in GB02, and FAT1 in GB03." (PMID 33922652, 2021). "In animal experiments, A549/DDP cells transfected with si-con, si-CHAF1B, and si-CHAF1B + si-NCOR2 respectively were transfected into mice for subcutaneous tumor transplantation." (PMID 32508530, 2020). "WB confirmed that the CHAF1B expression was up-regulated in the tissues of A549/DDP group, and NCOR2 was up-regulated in the tumor tissues in CHAF1B knockdown group." (PMID 32508530, 2020). "Multiple tumor-related NRs recruit NCOR2 for their functions, making NCOR2 a valuable target for cancer therapy." (PMID 32550907, 2020). "Both NCOR1 and NCOR2/SMRT were expressed at significantly lower levels in ER-negative tumours compared to ER-positive tumours (two-tailed Mann–Whitney U test: p < 0.001)." (PMID 31683867, 2019). "Overexpression of miR-100 and specific SMRT/NCOR2 targeted inhibition relating to tumor proliferation and apoptosis in vitro, and in vivo observations of reduced tumor size and improved animal tumor model survival were shown." (PMID 24244722, 2013).
tumor (continued). "Stable transfected GBM cell lines harboring an inducible miR-100 expression vector (miR-100 at two-three fold higher level than endogenous GBM levels) showed marked reduction of both Ki-67 proliferation by 40%, and SMRT/NCOR2 level by 70% in tumor xenografts." (PMID 24244722, 2013). "Since we identified SMRT/NCOR2 as a target for miR-100 inhibition, tumor xenograft brain sections were immuno-labeled with anti-SMRT/NCOR2 and anti-Ki-67." (PMID 24244722, 2013). "Overall, we report data showing anti-tumor role for miR-100 in GBM, and reveal that regulation of miR-100 levels, plus SMRT/NCOR2 and associated downstream pathways (e.g. HDAC3) are potential therapeutic targets for GBM." (PMID 24244722, 2013). "Both NCOR2 and CITED2 mRNA levels were associated with MFS, that is, tumour aggressiveness, independently of traditional prognostic factors." (PMID 19904269, 2009). "In a multivariate analysis including traditional prognostic factors (age, menopausal status, tumour size, grade and ESR1 and PGR mRNA levels), NCOR2 mRNA levels were significantly associated with a favourable MFS (median, HR=0.68, P=0.006) and OS." (PMID 19904269, 2009). "LncRNA PLANE (Pan-cancer LncRNA Activating NCOR2 responsive to E2F1) is up-regulated by copy number gain and E2F1-driven transcription activation, and then combines with NCOR2 pre-mRNA to modulate its alternative splicing, finally drives tumorigenesis and tumor propagation in various tumor types." (PMID 38933287, 2023). "Among them, altered NCOR2 expression has been reported and investigated in various tumours." (PMID 36497280, 2022). "Moreover, by using the Gene Expression Profiling Interactive Analysis Database, we found that the correlation between high NCOR2 levels and overall survival time was different in different tumours." (PMID 36497280, 2022). "Unsupervised clustering on the expression profiles issued from this series suggested two distinct subgroups: one composed of various molecular subtypes including CSF1 and FN1 rearranged samples and one composed of four tumors harboring an HMGA2::NCOR2 fusion, suggesting distinct tumor entities." (PMID 36439507, 2022). "MIR22HG was reported to decrease in HCC tissues and predict the poor prognosis of HCC patients, as it functions as a tumor suppressor and inhibits cell proliferation and invasion by sponging miRNA-10a-5p to upregulate nuclear receptor co-repressor 2 (NCOR2) expression." (PMID 34638971, 2021). "Given that NCOR2 are common corepressor for many tumor-related NRs including RARs and RXRs, targeting NCOR2 could have stronger anti-tumor effects than targeting RXR/RAR." (PMID 32550907, 2020). "If these observations translated to an in vivo situation, NCoR2 expression might have opposite prognostic implications according to the molecular milieu, tumor grading and stage of the disease." (PMID 29470550, 2018). "NCOR2-SCARB1 fusions were found in five different TCGA tumor types at a frequency < 2%." (PMID 28423358, 2017). "The importance of SMRT/NCOR2 to tumor cells was interrogated by reducing its expression in vitro." (PMID 24244722, 2013). "This confirms the importance of SMRT/NCOR2 as a tumor modulator in GBM lines." (PMID 24244722, 2013). "Our results showed that in LNN patients with ERα-positive primary tumours who had not received systemic adjuvant treatment, high mRNA levels of NCOR2 and CITED2 were associated with a longer MFS independently of the traditional prognostic factors." (PMID 19904269, 2009). "Two candidate target genes, CITED2 and NCOR2, yielding distinct gene expression profiles when compared with other cell lines, were analysed for their clinical relevance in terms of tamoxifen resistance and tumour aggressiveness." (PMID 19904269, 2009). "Notably, the roles of NCOR2 as a pro-oncogenic or tumour suppressor depend on the tumour types." (PMID 36497280, 2022).
tumor (continued). "Therefore, it can be speculated that NCOR2 may affect the biological function of tumour cells by regulating the expression of BDNF through NR4A1." (PMID 36497280, 2022). "In addition, we investigated that the expression of DHX37 was correlated with several tumor-related immune genes (PD-L1, TIM3, LAG3, TOX, RGS16, and NCOR2), indicating that it may play crucial roles in tumor immune dysregulation." (PMID 33490273, 2021). "Furthermore, the relapsed tumor acquired two relapse-specific mutations in USP54 and NCOR2." (PMID 26527318, 2016). "Therefore these data suggest that miR-100 has anti-tumor effect by modulating SMRT/NCOR2." (PMID 24244722, 2013). "This study demonstrates that BQ323636.1 (BQ) drives lipid metabolism in ER-positive breast cancer by upregulating ACSL4 through disruption of the NCOR2-PPARγ interaction, enhancing FAO to fuel tumor growth." (PMID 40507798, 2025). "The top-ranking genes included those that contribute to tumor development and drug resistance, such as AKT1, KLF6, and NCOR2." (PMID 37568192, 2023). "Low NCOR2 mRNA expression is positively correlated with shorter OS in LUAD patients, and downregulating NCOR2 promoted the expression of the tumor factors ELK1 and AXL." (PMID 38077434, 2023). "For a total of 471 cases of advanced GC, NCOR2, PARK2, and ZSCAN12 methylation statuses were determined in DNA samples obtained from tissue slides with representative tumor histology." (PMID 35039565, 2022). "Through genome-wide methylation profiling, NCOR2, PARK2, and ZSCAN12 were found to be highly methylated in CD3-positive and CD8-positive cells and rarely methylated in tumor cells." (PMID 35039565, 2022). "For three methylation markers, NCOR2, PARK2, and ZSCAN12, correlation of their methylation levels with the densities of CD3+ or CD8+ cells at the tumor center or invasive front was found." (PMID 35039565, 2022). "According to the data in TCGA tumor samples, the copy numbers of DHX37 were positively correlated with TIM3, LAG3 and NCOR2, while they were negatively correlated with PD-L1, RGS16 and TOX." (PMID 33490273, 2021). "The difference in DNA methylation between RFS and n/RFS primary tumours was less considerable, although a statistically significant difference was observed for DAXX, P<0.0001; RXRA, P<0.01; C8orf46, P=0.01; NCOR2 and MSI2 (P<0.05; t-test) enhancer regions." (PMID 26169690, 2015). "We show that BQ disrupts the NCOR2-PPARγ interaction, leading to ACSL4 upregulation, which enhances fatty acid oxidation (FAO), acetyl-CoA by 1.8-fold, and ATP production by 2.5-fold to fuel tumor proliferation." (PMID 40507798, 2025). "To test whether JUN’s ability to restrain tumor growth depends on NCOR1/2 expression, we cloned mirE-based tandem shRNA constructs targeting NCOR1 and NCOR2 into the myr-AKT-HA vector." (PMID 39210147, 2024). "SMRT/NCOR2 was silenced via siRNA and effects on tumor cells were analyzed in culture." (PMID 24244722, 2013). "Given the impact of the viral integrations within NCOR2 and CITED2 on the overall mRNA expression in our cell model, we established their relationships with clinical parameters reflecting tamoxifen resistance and tumour aggressiveness." (PMID 19904269, 2009). "The importance of the selection of study groups is illustrated by the fact that we did not observe a relationship between NCOR2 mRNA levels and MFS in patients with ERα-negative tumours (data not shown), contrasting with our findings in ERα-positive tumours." (PMID 19904269, 2009). "The NCOR2::GLI gene fusion present here is previously undescribed, the literature currently available generally emphasizes that SOX 10 is negative in these tumours, whereas this particular tumour was SOX 10 positive." (PMID 41035732, 2025).